TMEM185A (transmembrane protein 185A)
Synonyms: CXorf13; FAM11A; FRAXF; ee3
Tractability: Antibody: UniProt predicts a signal peptide or a membrane-spanning region.
Gene: Protein-coding gene on chromosome X (149,596,556 to 149,631,912, reverse strand). Ensembl gene ENSG00000269556.
Subcellular location: Cell projection, dendrite; Membrane
Subcellular location (Human Protein Atlas): Endoplasmic reticulum
Gene Ontology:
Molecular function: protein binding
Cellular component: dendrite; membrane
Homologues: Orthologues: chimpanzee TMEM185A (100% identical), mouse Tmem185a (99% identical), pig TMEM185A (99% identical), dog TMEM185A (96% identical), guinea pig TMEM185A (96% identical), rat Tmem185a (96% identical), tropical clawed frog tmem185a (95% identical), zebrafish tmem185 (88% identical). Paralogues in human: TMEM185B (88% identical), TMEM60 (9% identical).
Diseases named in the same sentence as TMEM185A in open-access papers:
TMEM185A is named in the same sentence as 4 diseases in open-access papers, as found by Europe PMC text mining. Sharing a sentence is not in itself a finding about the gene and the disease. The quoted sentences say what the papers report.
bladder cancer (1 paper, 2019). "And thirdly, we firstly identified a set of 4 genes (TMPRSS11E, SCEL, KRT78, TMEM185A) that were significantly associated with poor overall survival of bladder cancer patients, some of which have not been investigated in urinary bladder cancer before." (PMID 31737111, 2019).
fragile X syndrome (1 paper, 2016). A genetic syndrome caused by mutations in the FMR1 gene which is responsible for the expression of the fragile X mental retardation 1 protein. "This domain has been identified to be involved with the Fragile-X syndrome through the protein TMEM185A, however TMEM203 and TMEM60 share only ~10 % identity to the TMEM185A/B proteins and ~21 % identity between each other." (PMID 27030248, 2016).
TMEM185A also shares sentences with these, for which no sentence is quoted: serous ovarian carcinoma (2 papers); intellectual disabilities (1).